GRIA1 (glutamate ionotropic receptor AMPA type subunit 1)
Diseases named in the same sentence as GRIA1 in open-access papers (continued):
Sharing a sentence is not in itself a finding about the gene and the disease.
Anxiety (34 papers, 2010 to 2026). Intense feelings of nervousness, tension, or panic often arise in response to interpersonal stresses. "Male animals born from mothers fed the palatable diet, and who continued with this diet after weaning, exhibited anxiety associated with an overexpression of the mRNA of Grin1, Gria1 and Grm5 glutamate receptors in the prefrontal cortex." (PMID 32575416, 2020). "Knockout of GRIN2A and GRIA1 causes a decrease in anxiety in mouse models." (PMID 34763096, 2022). "Examining the mRNA SLC1A2, SLC1A3, GRM5, GRIN2B, GRIN2C, GRIA1, CHRNA7, 5-HT2A, and 5-HT3A offers insight into the neurotransmission systems implicated in NP-related anxiety." (PMID 41515464, 2026). "Multiple high-confidence ASD risk genes associated with anxiety were dysregulated in our RNA-seq data including TMLHE and GRID2, DNAH10, GRIA1, SLC6A4, and IGF1." (PMID 37486945, 2023). "GRIN2A and GRIA1 are two important glutamate receptors involved in the function of the sensorimotor cortex and also involved in anxiety." (PMID 34763096, 2022). "GRIK2 and GRIA1 have been confirmed as molecular basis of neurodegeneration and domestication-related behavioral alterations like fearfulness, anxiety, social exploration, learning and memory." (PMID 32131728, 2020). "Interestingly, GRIA1-/-knockout mice display hyperlocomotion, increased anxiety, exacerbated novelty response, and impaired spatial working memory and object recognition." (PMID 36460699, 2022). "Both, unconditioned anxiety on the EPM and— in stark contrast to the hyperlocomotion phenotype of Gria1−/− mice —novelty-induced locomotion in an open field were reduced in mice with hippocampal GluA1 knockout compared to their control group, but were unaffected by prefrontal GluA1 ablation." (PMID 35288531, 2022).
Alzheimer disease (24 papers, 2009 to 2025). A progressive, neurodegenerative disease characterized by loss of function and death of nerve cells in several areas of the brain leading to loss of cognitive function such as memory and language. "Indeed, p97/Gab2 is required for the PI3K/AKT1 signaling pathway and p97/Gab2-mediated PI3K/AKT1 activation is involved in the pathogenesis of Alzheimer’s disease (AD) that shows the reduced GRIA1 surface expression." (PMID 32781725, 2020). "High-priority targets include established therapeutic genes such as IGF1, for which mecasermin represents an existing FDA-approved treatment, and GRIA1/GRIN2A, which are targeted by memantine and other glutamate receptor modulators currently used in Alzheimer’s disease management." (PMID 41155297, 2025).
migraine (14 papers, 2010 to 2025). "In the past, researchers have paid more attention to the association between the GRIA1 gene and migraine, but recently they have begun to turn their attention to the role of the GRIA1 gene in tumor biology." (PMID 35936688, 2022). "There was a significant association between GRIA1 rs2195450 C>T polymorphism and migraine risk under heterozygous model (CT vs. CC, OR = 1.23, 95%CI = 1.02–1.48, PZ = 0.03)." (PMID 30446525, 2018). "As far as we know, this is the first meta-analysis reporting the association of GRIA1 rs548294 G>A and rs2195450 C>T polymorphisms and migraine risk." (PMID 30446525, 2018). "GRIA1 rs2195450 C>T polymorphism was significantly associated with migraine risk under heterozygous model (CT vs. CC, OR = 1.23, 95%CI = 1.02–1.48, PZ = 0.03)." (PMID 30446525, 2018). "Our results indicates that GRIA1 rs2195450 C>T polymorphism is significantly associated with migraine risk." (PMID 30446525, 2018). "The result showed that the omission of any one study did not significantly change the overall estimation result on the association between GRIA1 rs548294 G>A polymorphism and migraine risk." (PMID 30446525, 2018). "Our data of this study confirmed the association of GRIA1 (rs2195450) to female migraine (MA, MO) susceptibility in the Chinese Han population." (PMID 26800698, 2015). "The result also provides evidence that the glutamatergic system, particularly the GRIA1 gene, is implicated in the pathophysiology of migraine." (PMID 26800698, 2015). "In our present study, a statistically significant finding is that the GRIA1 rs2195450 variant is a potential genetic risk factor for female migraine in the Chinese Han population from the southern Fujian province of China." (PMID 26800698, 2015). "This study is the first report of rs2195450 SNP in GRIA1 gene associated with female migraine (MA, MO) in Chinese Han population." (PMID 26800698, 2015). "Nonetheless, an even larger scale case-control study in populations of different origin should be performed to evaluate the association of the GRIA1 rs2195450 variant to migraine susceptibility." (PMID 26800698, 2015). "However, the result of Fang’s study indicated that the GRIA1 rs2195450 C>T polymorphism was significantly associated with migraine risk." (PMID 30446525, 2018). "In order to confirm this hypothesis, some case–control studies were conducted to investigate the association of GRIA1 polymorphisms (rs548294 G>A, rs2195450 C>T) with migraine risk." (PMID 30446525, 2018). "Thus GRIA1 polymorphisms may also be involved in migraine risk." (PMID 30446525, 2018). "GRIA1 and GRIA3 (subunits GluR1 and GluR3) gene polymorphisms are considered potential predisposing/causative factors for migraine." (PMID 27191890, 2016). "Another association analysis on Italian population have reported two genes that code for subunits of the ionotropic AMPA receptors GRIA1 and GRIA3 have been implicated in migraine." (PMID 26800698, 2015). "They discovered that the rs548294 variant of the GRIA1 gene was associated primarily with the migraine without aura phenotype." (PMID 34148407, 2021). "Further subgroup analysis based on ethnicity showed a significant association of GRIA1 rs2195450 C>T polymorphism with migraine risk in Asian population, but not in Caucasian population." (PMID 30446525, 2018). "Further stratified analysis based on ethnicity also showed no statistical association between GRIA1 rs548294 G>A polymorphism and migraine risk under all genetic models." (PMID 30446525, 2018). "Common variants in the regulatory regions of the GRIA1 gene showed a strong association with migraine patients with and without aura." (PMID 25915028, 2015). "Two SNPs in GRIA1 (5q33.2, rs548294 MO allelic P=0.008, rs2195450 MA allelic P=0.0005) and 1 SNP in GRIA3 (rs3761555 MA Females allelic P=0.003) showed a positive association with migraine." (PMID 23675283, 2013).
migraine (continued). "We found two variants in GRIA1 gene (rs548294 and rs2195450) and one variant in GRIA3 gene (rs3761555), all located in the regulative region of the genes, to be associated with the migraine phenotype in an Italian population." (PMID 20579352, 2010). "Frequency of common GRIA1 haplotypes in migraine patients compared with healthy controls." (PMID 20579352, 2010). "Therefore, GRIA1 gene was inferred as a migraine-related gene." (PMID 30446525, 2018). "Subgroup analysis based on ethnicity showed a significant association of GRIA1 rs2195450 C>T polymorphism with migraine risk in Asian population, but not in Caucasian population, suggesting that the effect of this polymorphism might depend on genetic background of different ethnicities." (PMID 30446525, 2018). "In contrast, CALCA and PRDM16 polymorphisms showed moderate evidence, and GRIA1 and SCN1A showed weaker evidence to explain nonresponsive migraine patients to Triptan treatment." (PMID 41121943, 2025). "Further remarkable in our cohort is that GRIA1 and GRIA3 variants are associated to migraine in female but not in male subjects." (PMID 20579352, 2010). "Furthermore, our analysis of the combined effects of the two SNPs in GRIA1 (rs548294) and GRIA3 (rs3761555) genes not supported a synergy of the two SNPs in the genetic susceptibility to migraine." (PMID 20579352, 2010). "In this study we investigated the association of GRIA1, GRIA2, GRIA3 and GRIA4 genes that encode for the four subunits (GluR1-GluR4) of the alpha-amino-3-hydroxy-5-methyl-4-isoxazole-propionic acid (AMPA) ionotropic receptor and their variants to migraine with and without aura (MA and MO)." (PMID 20579352, 2010).
glioma (11 papers, 2013 to 2026). A benign or malignant brain and spinal cord tumor that arises from glial cells (astrocytes, oligodendrocytes, ependymal cells). "In addition, GRIA1 is an ionotropic receptor for glutamate signaling, and has been proved to promote the growth of glioma tumor cell." (PMID 37189138, 2023). "Indeed, the combination of GRIA1 as well as FAK inhibitors had a synergistic effect on tumor cell migration, suggesting another aspect of epigenetically regulated glioma phenotypes." (PMID 38481314, 2024). "GRIA1 and GRIA3 were shown to promote tumor progression in glioma and pancreatic cancer." (PMID 25326682, 2014).
Stroke (10 papers, 2018 to 2025). Sudden impairment of blood flow to a part of the brain due to occlusion or rupture of an artery to the brain. "We showed that the expression of Dlg4, Gria1, Grin2a, Gng3, Gnb5, MapK8, and Bdnf (encoding PSD-95, GluA1, GluNMDA2A, G-protein subunit gamma 3, G-protein subunit beta 5, JNK, and BDNF, respectively) was strongly reduced 1 week after stroke." (PMID 31888302, 2019).
glioblastoma (8 papers, 2014 to 2024). The most malignant astrocytic tumor (WHO grade IV). "To sum up, we identified seven genes (GRIA1, GRIA2, GRIK1, GRIK4, GRM3, GLUL, BCAT1) whose mRNA expression may serve as potential molecular biomarker candidates to distinguish glioblastoma and brain metastases tissue derived from surgical resections." (PMID 38835368, 2024).
autism (7 papers, 2013 to 2025). Persistent deficits in social interaction and communication and interaction as well as a markedly restricted repertoire of activity and interest as well as repetitive patterns of behavior. "We show here that the CACNA1I risk variant induces spindle deficits, which corroborated with two recent studies of PTCHD1 and GRIA1, two genes implicated by neuropsychiatric genetics, that abnormal sleep spindle oscillation may underlie neurodevelopmental disorders such as autism and schizophrenia." (PMID 32066662, 2020). "Importantly, de novo missense variants affecting the M3 channel gate or the M3-S2 linkers have been previously identified in several iGluR subunit genes (e.g., GRIA1, GRIA3, and GRIA4); phenotypes of these patients include ID, autism and epilepsy." (PMID 31300657, 2019).
bipolar disorder (7 papers, 2014 to 2022). A disorder of the brain that causes unusual shifts in mood, energy, activity levels and the ability to carry out day-to-day tasks. "A mouse line with deficient AMPA-type glutamate receptor GluA1 subunits [the Gria1-/- mouse line] has been proposed as an animal model for hyperactive disorders, including schizoaffective disorder and bipolar disorder with mania." (PMID 30984001, 2019).
cognitive decline (6 papers, 2018 to 2025). "The reduced m6A levels in aged mice have been found to lead to a decrease in synaptic protein calcium/calmodulin dependent protein kinase II (CAMK II) and glutamate ionotropic receptor AMPA type subunit 1 (GLUA1) synthesis during cognitive decline." (PMID 37762200, 2023).
Allergy (4 papers, 2015 to 2023). An allergy is an immune response or reaction to substances that are usually not harmful. "In another GWA study, a germline genetic variant, rs4958351, in the GRIA1 gene, associated with an asparaginase allergy in pediatric ALL patients, was identified." (PMID 30832275, 2019). "In this study variants of the GRIA1 (Glutamate Receptor, Ionotropic, AMPA 1) gene located at 5q33 have been found associated with ASP allergy." (PMID 26457809, 2015). "ATF5 and EFS, ASNS and allergy/pancreatitis, GRIA1 and hypersensitivity, HLA-DRB1*0701 and allergy, CPA2 and pancreatitis)." (PMID 28574850, 2017). "The aim of our study was to investigate the impact of genetic variants of GRIA1 and GALNT10 genes on ASP allergy in a large Hungarian population of 576 ALL patients." (PMID 26457809, 2015). "Neither ASNS- or GRIA1- analyzed variants nor ancestry were significantly associated with L-ASP allergy." (PMID 38044950, 2023).
Intellectual disability (4 papers, 2019 to 2023). "Pathogenic variants of GRIA1–4 have been described in patients with developmental delay, intellectual disability, autism spectrum disorder, and seizures, with GRIA2 variants typically causing AMPAR loss of function." (PMID 36161652, 2022).
Parkinson disease (4 papers, 2010 to 2014). A progressive degenerative disorder of the central nervous system characterized by loss of dopamine producing neurons in the substantia nigra and the presence of Lewy bodies in the substantia nigra and locus coeruleus. "GRIA1 is linked with spatial learning and memory whereas SNCA is linked with Parkinson disease." (PMID 24523945, 2014). "Some of the players in the outlined route like ADAM17, CX3CL1, DRD1, GRIA1, and LCAM1 have been claimed in animal model studies as therapeutic targets for Parkinson's disease." (PMID 24688734, 2013).
psychosis (4 papers, 2018 to 2025). "Notably, GluA1 deficient mice (Gria1−/− mice) exhibit impaired hippocampal synaptic plasticity, and extensive behavioural studies have revealed deficits in habituation and attention, relevant for psychosis aetiology." (PMID 30108203, 2018). "Deficiency in prepulse inhibition of an acoustic startle reflex is indicative of psychosis-related properties and increased learned helplessness as deficits in coping skills in aversive situations indicative of depressive phenotype of Gria1-/- mice." (PMID 30984001, 2019).
schizoaffective disorder (4 papers, 2010 to 2022). "Despite that the dopaminergic dysfunction has a recognized role in schizoaffective disorders and might play a role in Gria1-/- mice, there is evidence rather pointing to indirect effects of cannabinoids on dopamine cell firing, by altering glutamate neurotransmission." (PMID 30984001, 2019).
diabetes (3 papers, 2009 to 2025). "However, Wistar rats showed no change in GRIA1 transcript levels after 1, 4, and 12 weeks of diabetes." (PMID 23878504, 2013).
acute lymphoblastic leukemia (2 papers, 2022). Leukemia with an acute onset, characterized by the presence of lymphoblasts in the bone marrow and the peripheral blood. "Some scholars have found that the GRIA1 gene affects the prognosis of children with acute lymphoblastic leukemia." (PMID 35936688, 2022).
amyotrophic lateral sclerosis (2 papers, 2019 to 2023). Amyotrophic lateral sclerosis (ALS) is a neurodegenerative disease characterized by progressive muscular paralysis reflecting degeneration of motor neurons in the primary motor cortex, corticospinal tracts, brainstem and spinal cord. "In our study, we found that GRIA1 was involved in two pathways, which were over-represented for F. hepatica-damaged liver and are linked to the neurology of the animal, amyotrophic lateral sclerosis, and neuroactive ligand-receptor interaction." (PMID 30999842, 2019).
Ataxia (2 papers, 2017 to 2022). Ataxia refers to impaired coordination of voluntary muscle movement. "Gria1 overexpression via intracerebroventricular delivery of adeno-associated virus (AAV) rescued motor deficits in ataxia mice." (PMID 36064798, 2022). "We therefore speculate that synaptic dysfunction associated with downregulation of cerebellar Gria1 in ataxia mice and patients with ataxic manifestations, leading to motor deficits after PNI." (PMID 36064798, 2022). "In this study, we report for the first time that there is a potential mechanistic link between Gria1 and spontaneous motor recovery in patients with ataxia due to the glutamatergic dysfunction." (PMID 36064798, 2022). "Compared with AAV-eGFP-treated ataxia mice, we observed a nearly 3-fold increase in mRNA expression of Gria1 in the DCN of AAV-Gria1-treated ataxia mice." (PMID 36064798, 2022). "Together, these data indicate that GRIA1 plays an important role in spontaneous motor function recovery after PNIs, especially in patients with clinical manifestations that include ataxia." (PMID 36064798, 2022). "Two weeks before the SNC, adeno-associated virus serotype 2 (AAV2) overexpressing mouse Gria1 (AAV-Gria1) was intracerebroventricularly injected into the DCN of ataxia mice." (PMID 36064798, 2022). "AAV-mediated overexpression of Gria1 in DCN rescued motor deficits of ataxia mice after PNI." (PMID 36064798, 2022). "Finally, we asked whether increasing the expression level of Gria1 in the DCN of ataxia mice could rescue motor deficits in the ataxia mice after SNC." (PMID 36064798, 2022). "Strikingly, overexpression of Gria1 completely restored motor deficits in ataxia mice and comparable to that in the AAV-eGFP-control mice after a single SNC, while the AAV-eGFP-treated ataxia mice were unable to return to baseline motor function." (PMID 36064798, 2022). "Interestingly, mRNA expression of Gria1 was upregulated in control mice but remained unchanged in ataxia mice after SNC, suggesting a potential role in spontaneous motor recovery of ataxia mice after PNIs." (PMID 36064798, 2022). "Transcriptomic study revealed that Gria1, an ionotropic glutamate receptor, was upregulated in DCN of control mice but failed to be upregulated in ataxia mice after sciatic nerve crush." (PMID 36064798, 2022).
atherosclerosis (2 papers, 2021 to 2025). A disease characterized by the build-up of fatty material and calcium deposition in the arterial wall resulting in partial or complete occlusion of the arterial lumen. "Whereas, a previous study has shown that low mRNA level of GRIA1 is associated with atherosclerosis in vascular smooth muscle cells." (PMID 40692577, 2025). "GRIA1 and GRIA2 mRNA levels correlated positively with the inferred relative abundance of VSMCs and negatively with the inferred abundance of T cells and macrophages in plaques, further supporting an association between AMPA-type glutamate receptors and VSMCs in atherosclerosis." (PMID 33959644, 2021).
bladder cancer (2 papers, 2021 to 2022). "For example, GRIA1 serves as a prognosticators for basal-like bladder cancer." (PMID 35675043, 2022).
brain tumor (2 papers, 2014 to 2024). "In this context, nestin, BLBP and GRIA1 are potential biomarkers predicting sensitivity to this drug in brain tumor cells." (PMID 25531110, 2014). "First, two ionotropic AMPA receptors, GRIA1 and GRIA2 were found to be higher expressed in primary brain tumors." (PMID 38835368, 2024).